MAPT (microtubule associated protein tau)
Diseases named in the same sentence as MAPT in open-access papers (continued):
Sharing a sentence is not in itself a finding about the gene and the disease.
frontotemporal dementia (continued). "The ability of BPN-15477 to promote the exclusion of exon 10 in the MAPT gene is particularly exciting given its role in frontotemporal dementia." (PMID 34099697, 2021). "Pathogenic mutations in the TAU-encoding MAPT gene underlying familial frontotemporal dementia (FTD), such as TAUP301L or TAUP301S, have supported the generation of multiple mouse models that recapitulate pathological and/or behavioural aspects of this disease." (PMID 34001284, 2021). "Mutations in the MAPT gene cause frontotemporal dementia (FTD)." (PMID 34158384, 2021). "Frontotemporal lobar degeneration (FTLD)-MAPT-P301L patients with different clinical phenotypes also displayed three signatures, two resembling those found in TgTauP301L mice." (PMID 32219515, 2020). "Reduced basal forebrain volumes were also seen in MAPT mutations (18%, p < 0.0005) and in individuals with pathologically confirmed FTDP-17 (17%), Pick's disease (12%), and TDP-43 type C (8%) (p < 0.001)." (PMID 32143137, 2020). "We also included EPHA4, for which only one functional involvement in ALS has been described recently, GRN and MAPT, which are both more likely frontotemporal dementia (FTD)-related genes." (PMID 32987860, 2020). "MAPT mutations/FTDP-17, Pick's disease, and transactive response DNA binding protein 43 kDa type C were the forms with the smallest amygdala (35%–50% smaller than controls in the most affected hemisphere, P < .0005)." (PMID 30788410, 2019). "Another inherited neurodegenerative disease involving protein aggregation includes frontotemporal dementia (FTD), which is caused by mutations in either the microtubule-associated protein Tau (MAPT:FTDP - 17MAPT) or the progranulin (PGRN:FTDP - 17PGRN) genes." (PMID 31795242, 2019). "Moreover, pathological deposition of hyperphosphorylated MAP-tau (MAPT), which is the hallmark of several neurodegenerative disorders such as AD and frontotemporal dementia (FTD), has been described in elderly subjects with schizophrenia." (PMID 30061532, 2018). "Genomic DNA was obtained, and APP, PSEN1, PSN2, and APOE genes associated with AD, PGRN, MAPT, VCP, CHMP2B, TARDBP, and C9ORF72 genes associated with frontotemporal lobar degeneration were screened for mutations by sequencing." (PMID 29503630, 2018). "In 1998, frontotemporal dementia associated with parkinsonism was linked to chromosome 17 (FTDP-17), leading to the discovery of the microtubule-associated protein tau gene (MAPT) in 1998 and of the progranulin gene (GRN) in 2006." (PMID 29370838, 2018). "Genes that are part of this pathway have previously been implicated in various neurological diseases such as Parkinson’s disease (PARK2), frontotemporal dementia (MAPT), neurofibromatosis 2 (NF2), tuberous sclerosis (TSC1)." (PMID 30258056, 2018). "Genetic frontotemporal dementia is most commonly caused by mutations in the progranulin (GRN), microtubule-associated protein tau (MAPT) and chromosome 9 open reading frame 72 (C9orf72) genes." (PMID 28529873, 2017). "Astroglial pathology is seen in various neurodegenerative diseases including frontotemporal dementia (FTD), which can be caused by mutations in the gene encoding the microtubule-associated protein TAU (MAPT)." (PMID 28256506, 2017). "Disturbance of the 3R/4R ratio of MAPT has been evident in neurodegenerative diseases such as Frontotemporal dementia (FTD), Corticobasal degeneration (CBD), Progressive supranuclear palsy (PSP) and AD." (PMID 23805206, 2013). "Genome editing of MAPT locus to model frontotemporal dementia." (PMID 40219788, 2025). "While not present in AD, MAPT gene mutations cause tau accumulation in hyperphosphorylated, conformationally altered, and aggregated form, leading to neurodegeneration, e.g. in frontotemporal dementia." (PMID 40027607, 2025).
frontotemporal dementia (continued). "Mutations in the tau gene MAPT, located on chromosome 17, are linked to several tauopathies, including progressive supranuclear palsy (PSP), corticobasal degeneration (CBD), Pick disease (PiD), and frontotemporal dementia (FTD)." (PMID 38733347, 2025). "In this study, we describe mouse models of FTD that exhibit hyperphosphorylated tau, synapse loss, neuritic degeneration, and cognitive and behavioral abnormalities, replicating common features observed in patients with MAPT-FTLD (frontotemporal lobar degeneration)." (PMID 39719507, 2025). "Moreover, frontotemporal lobar degeneration (FTLD) with GRN pathogenic variants experience faster progression of atrophy than C9orf72-FTLD and MAPT-FTLD." (PMID 39920674, 2025). "This is despite the absence of specific MAPT mutations in these conditions, except for frontotemporal dementia." (PMID 38646816, 2024). "The responsible pathogenic mutation usually resides in one of the three major genes causing frontotemporal dementia: progranulin (GRN) (the most frequent genetic cause), chromosome 9 opening reading frame 72 (C9orf72) or (rarely) microtubule-associated protein tau (MAPT)." (PMID 37906327, 2024). "Our specific aim was to evaluate glymphatic system abnormalities in presymptomatic and symptomatic individuals with pathogenic mutations within the MAPT, GRN and C9orf72 genes, to provide novel insight into the pathophysiology of genetic frontotemporal dementia." (PMID 39015769, 2024). "Subsequently, we analyzed PRDM16-DT expression in postmortem brain tissues (frontal lobe) obtained from patients with frontotemporal dementia (FTD) carrying mutations in C9ORF72, GRN, or MAPT genes, as well as from control individuals that are available via the RiMOD database." (PMID 39207536, 2024). "Notably, another predominantly 4R tau tauopathy-frontotemporal lobar degeneration (FTLD)-MAPT-P301L-also displays three distinct tau signatures in cases with different clinical phenotypes, two resembling those found in prodromal TgTauP301L mice model of FTLD." (PMID 36230957, 2022). "It is important to note, however, that mutations in the MAPT gene cause frontotemporal dementia but have not been linked to AD directly, therefore the interpretation of these results in the context of AD must be taken with caution." (PMID 35732622, 2022). "Missense mutations in MAPT, the gene coding for Tau, can result in familial forms of frontotemporal dementia but are not causative of AD." (PMID 34503576, 2021). "One of the mutations in the microtubule-associated protein tau, P301S, is causative for dominantly inherited frontotemporal dementia characterized by extensive tau pathology for which no licensed treatment is available." (PMID 34366349, 2021). "GLT1 (EAAT2) expression is markedly reduced in most astrocytes bearing hyper-phosphorylated tau in a rare familial behavioural variant of frontotemporal dementia associated with astrocyte-predominant tauopathy not linked to mutations in MAPT." (PMID 31907603, 2020). "The present study has referred to several genes associated with AD and frontotemporal lobar degeneration, but those genes including MAPT have been confirmed negative; however, his CSF biomarker screening has revealed possible tau pathology." (PMID 29503630, 2018). "Case reports of non-AD tauopathies such as frontotemporal dementia with MAPT mutation P301L, suspected CTE, PSP, and CBS also demonstrated elevated binding of 18F-T807 in frequent areas of tau aggregates in those conditions." (PMID 26751494, 2016). "Mouse models of tauopathy overexpress mutated human MAPT (which is causal for frontotemporal dementia, not AD) to induce tau pathology, and do not exhibit amyloid aggregation." (PMID 27622770, 2016).
frontotemporal dementia (continued). "Building on recent genetic discoveries, Julie Snowden (University of Manchester, UK) showed the relationship between the diverse clinical characteristics and the underlying pathologies of frontotemporal dementia (FTD) (tau, TDP-43 and FUS) and associated genetic mutations (MAPT, C9orf72 and GRN)." (PMID 27391874, 2015). "Furthermore, mutations in the genes associated with frontotemporal lobar degeneration (FTLD), namely the microtubule-associated protein tau (MAPT) and progranulin (GRN) genes were also found to be associated to clinical AD." (PMID 25333068, 2014). "Tg(MAPT,P301S) mice do not show decreased Sho levels in their brains despite expressing mutant human tau causing frontotemporal dementia." (PMID 22163178, 2011). "Since the first genetic linkage study identified the existence of MAPT gene mutations with familial FTLD, a significant amount of effort has been invested into the identification of novel genes associated with frontotemporal dementia, the second most common cause of senile dementia." (PMID 22654721, 2011). "Mutations in the gene encoding microtubule-associated protein tau (MAPT) typically present with a frontotemporal dementia phenotype with or without a parkinsonian syndrome—hence the clinical nomenclature of FTDP-17." (PMID 19175287, 2009). "Several MAPT mutations, such as P301S and S305N, as well as splicing variants like IVS 10 + 16, result in frontotemporal dementia (FTD) 6,41–44." (PMID 41255983, 2025). "In frontotemporal dementia (FTD), elevated OPN levels in MAPT-mutant neurons are associated with impaired graft survival and reactive gliosis, whereas knockdown of OPN improves integration and reduces inflammatory responses." (PMID 41009647, 2025). "The Genetic Frontotemporal Dementia Initiative (GENFI) is a group of research centres across Europe and Canada investigating genetic forms of FTD, focusing on mutations in the GRN, microtubule-associated protein tau (MAPT) and C9orf72 genes." (PMID 36718490, 2024). "Inherited mutations in the MAPT gene, which encodes TAU, are linked to familial frontotemporal dementia (FTD)." (PMID 39931431, 2024). "Finally, genetic testing for mutations in genes commonly associated with frontotemporal lobar degeneration (FTLD) (MAPT, GRN, C9orf72) was negative." (PMID 33310885, 2020). "In a study of frontotemporal dementia (FTD), symptomatic FTD patients with GRN mutation had more WMH load than patients with microtubule-associated protein tau (MAPT) and chromosome 9 open reading frame 72 (C9orf72) gene mutations." (PMID 33352859, 2020). "For example, patient-specific iPSCs were used to create a disease model of frontotemporal dementia (FTD), wherein CRISPR Cas9 was used to introduce mutations in the MAPT gene." (PMID 32671050, 2020). "Facial Emotion Recognition (FER) and Faux Pas (FP) recognition tests were used to study social cognition within the Genetic Frontotemporal Dementia Initiative (GENFI), a large familial FTD cohort of C9orf72, GRN, and MAPT mutation carriers." (PMID 33221702, 2020). "Interestingly, although a diagnosis of SD in association with a frontotemporal dementia genetic abnormality is rare, semantic impairment appears to develop quite commonly in individuals carrying a mutation in the GRN or microtubule associated protein tau (MAPT) genes." (PMID 27915998, 2016). "However, changes in several other genes have been suggested as causes for recessive neurological/neurodegenerative disorders that may include PD: hereditary ataxias (ATXN2/3, FMR1), frontotemporal dementia (e.g. MAPT) and others (e.g. ATP13A2, PLA2G6, FBXO7)." (PMID 23976986, 2013). "Additionally, mutations in the MAPT and GRN genes—commonly associated with frontotemporal dementia (FTD), a condition that disproportionately affects younger individuals—were analyzed." (PMID 40725212, 2025).
frontotemporal dementia (continued). "While mutations in APP, PSEN1, and PSEN2 in the Aβ-generation pathway may lead to familial AD showing plaques and tangles, mutations in MAPT may lead to tangle formation but not plaques, resulting in frontotemporal dementia (FTD) or conditions similar to CBD, PSP, or PiD." (PMID 38732197, 2024). "The commonly used triple mutant 3xTg-AD mouse model contains two mutations associated with familial AD, APP (KM670/671NL; Swedish), and PSEN1 (M146V), and one with fronto-temporal dementia (FTD), MAPT (P301L)." (PMID 37264120, 2023). "Frontotemporal dementia (FTD) is a common form of young-onset dementia and is frequently caused by autosomal dominant genetic mutations in progranulin (GRN), chromosome 9 open reading frame 72 (C9orf72) or microtubule-associated protein tau (MAPT)." (PMID 36064709, 2022). "Similar to other neurodegenerative diseases, frontotemporal dementia (FTD) may have familial forms, which are associated with mutations in the genes coding for progranulin (GRN), chromosome 9 open reading frame 72 (C9orf72), or microtubule-associated protein tau (MAPT)." (PMID 34108859, 2021). "Next, we screened the genes related to Perry syndrome, frontotemporal dementia (FTD), such as DCTN1, and MAPT by Sanger sequencing and C9orf72 by the repeat-primed PCR." (PMID 32854784, 2020). "For example, for subjects carrying the MAPT, GRN, or C90rf72 genotypes, the concentration of NFL in cerebrospinal fluid (CSF) was increased after the onset of frontotemporal dementia (FTD)." (PMID 32530970, 2020). "A key hallmark of major neurodegenerative disorders—including Alzheimer’s disease (AD), amyotrophic lateral sclerosis (ALS), frontotemporal dementia (FTD), synucleinopathies and prion diseases—is the intracellular accumulation of aggregated proteins such as MAPT, TDP43, FUS, PRNP and SNCA." (PMID 41278186, 2025). "In this study, we investigated a panel of CSF synaptic markers in presymptomatic and symptomatic people with genetic FTD from the GENetic Frontotemporal dementia Initiative (GENFI), hypothesizing that we would find differential abnormalities across MAPT, GRN, and C9orf72 mutation carriers." (PMID 36045450, 2022). "However, unlike mutations in APP and APP processing genes, mutations in MAPT typically result in in a different type of dementia called frontotemporal dementia (FTD) rather than FAD." (PMID 33255414, 2020). "Frontotemporal dementia (FTD) is a common cause of dementia with around one-third of cases being familial, most commonly caused by mutations in 1 of 3 genes: chromosome 9 open reading frame 72 (C9orf72), progranulin (GRN), and microtubule-associated protein tau (MAPT)." (PMID 29172163, 2018). "In Pick’s disease, PSP, CBD, and most cases caused by MAPT mutations, Tau filaments do not accumulate to a significant extent in the extracellular space following the death of aggregate-bearing cells." (PMID 29497399, 2018). "Given the significant overlap in clinical presentation, individuals with a strong family history of AD should also be screened for mutations in MAPT and GRN, genes typically associated with frontotemporal lobar degeneration, when no autopsy is available." (PMID 22312439, 2012). "Interestingly, our results identified several loci that have been previously associated with the risk of Parkinson’s disease (e.g.: LRRK2, ITKB, CCDC62), but no loci overlapping with frontotemporal dementia in addition to the MAPT locus." (PMID 35589863, 2022). "Interestingly, an individual with frontotemporal dementia (FTD) was found to have a partial deletion of the MAPT gene, resulting in the production of truncated tau lacking the first microtubule-binding repeat." (PMID 32728795, 2020). "Interestingly, although MAPT mutations are linked with other types of human dementia, such as frontotemporal dementia (FTD) and corticobasal degeneration (CBD), no MAPT mutation is found to be associated with AD." (PMID 24278307, 2013).
frontotemporal dementia (continued). "Mutations in the human MAPT gene (microtubule associated protein tau), which codes for the human TAU (hTAU) protein, cause frontotemporal dementia (FTD), but not AD." (PMID 34884970, 2021). "Given the patient’s family history of frontotemporal dementia (FTD) in a maternal uncle, the genetic analysis was extended to include the most common genes associated with FTD (TARDBP, GRN, TBK1, CHMP2B, SQSTM1, UBQLN2, VCP and MAPT) but no additional variants of clinical significance were detected." (PMID 40659544, 2025).
Parkinson disease (276 papers, 2004 to 2025). A progressive degenerative disorder of the central nervous system characterized by loss of dopamine producing neurons in the substantia nigra and the presence of Lewy bodies in the substantia nigra and locus coeruleus. "MAPT mutations seem to be highly penetrant, as a family history of parkinsonism or dementia is frequently observed among MAPT mutation carriers." (PMID 40722695, 2025). "Lipids are implicated in the pathogenesis of a number of neurodegenerative diseases, but few reports have explored how MAPT mutations, known to cause parkinsonism and FTLD, affect brain lipid metabolism." (PMID 41318029, 2025). "The MAPT locus on chromosome 17, for instance, was concurrently associated with AD, Parkinson’s disease, and circulating total-tau." (PMID 41296471, 2025). "Several autosomal dominant mutations in the MAPT/TAU gene have been found to cause FTD with parkinsonism linked to chromosome 17, which is characterized by the presence of filamentous MAPT/TAU inclusions (FTLD-tau) in the atrophic frontal and temporal lobes." (PMID 39684697, 2024). "Mutations in the gene encoding microtubule associated protein tau cause neurodegeneration in the form of frontotemporal dementia and parkinsonism linked to chromosome 17, which result in tau pathology that lacks β-amyloid deposits." (PMID 38987603, 2024). "MAPT has been found to be a causative protein in several psychiatric disorders and Parkinson’s disease." (PMID 38904036, 2024). "Elements of parkinsonism and basal ganglia degeneration were noted also in the case of MAPT p.K298E mutation described by Iovino in 2014 (notably, with a normal DaT-Scan)." (PMID 38592608, 2024). "Individuals with pathological MAPT variants exhibit behavioural changes, cognitive impairment and signs of parkinsonism." (PMID 39185206, 2024). "Concerning Parkinson's disease, it has been suggested that age and the H2 variant of the MAPT gene are associated with an increased risk, as well as lower overall MAPT expression." (PMID 39351424, 2024). "Behavioral symptoms are the most common clinical manifestation, but in some cases, MAPT mutations are also associated with parkinsonism." (PMID 38073060, 2024). "A Parkinson’s disease GWAS study found that MAPT was a significant risk locus for Parkinson’s disease that is uncoupled from the age of onset." (PMID 38895329, 2024). "ALS is extremely rare in those with GRN or MAPT mutations but a substantial minority can present with parkinsonism." (PMID 36385202, 2023). "Parkinson’s disease has a higher prevalence among males due to the methylation profile of sex-specific genes such as microtubule-associated protein tau (MAPT)." (PMID 38239489, 2023). "In contrast, GRN and MAPT mutation carriers had fewer individuals with symptoms, although in those who did have motor impairment, features were suggestive of parkinsonism (with fewer bulbar symptoms)." (PMID 36385202, 2023). "The same group reported parkinsonism and hand tremor co-occurring with behavioural presentation in one of eight patients with MAPT p.P301L (c.902C > T) variant." (PMID 37746582, 2023). "In 1990, mutations in MAPT gene were associated with an autosomal inherited form of FTD with parkinsonism; this was the first evidence of a genetic cause for familial FTD." (PMID 37511491, 2023). "Other genes excluded from the PARK category, such as GBA1, GTP cyclohydrolase 1 (GCH1), and MAPT, were also significantly linked to PD or parkinsonism through meta-analyses of GWAS." (PMID 35720097, 2022). "Patients with MAPT mutations showed middle-aged onset of progressive parkinsonism and cognitive decline with a high penetrance ratio." (PMID 35720097, 2022). "One of the genes affected by the inversion polymorphism is MAPT, a candidate gene in Parkinson’s disease." (PMID 36415660, 2022). "The first mutation in its coding gene microtubule associated protein tau (MAPT) was found to be causative of FTD linked with parkinsonism in 1998." (PMID 32770783, 2021).